ALB (albumin)
Diseases named in the same sentence as ALB in open-access papers (continued):
Sharing a sentence is not in itself a finding about the gene and the disease.
sarcopenia (continued). "However, ALT and albumin in serum were comparable between cirrhotic patients with and without sarcopenia in both sexes." (PMID 37767786, 2023). "However, their albumin, total cholesterol, and triglyceride levels were lower than those without sarcopenia." (PMID 38131980, 2023). "In a second step, we compared the evolution of physical performance between faller and no-faller, between those with > 1 sarcopenia/fall risk factors vs. ≤ 1 indicator, and patients with the normal inflammatory indicator (CRP ≤ 30 mg/l and albumin ≥ 30 g/l), and those with subnormal value." (PMID 35186984, 2022). "Systemic albumin levels are not only used as a prominent nutritional biomarker, mainly in aged people, but increased blood albumin levels were previously reported in the older adult population who did not present with sarcopenia and frailty as compared to those who presented with these conditions." (PMID 36141348, 2022). "In addition to sarcopenia, our newly proposed scoring system also included factors such as multiple tumors, maximal tumor diameter≥ 5cm, major venous thrombosis, AFP ≥ 200 ng/ml, and albumin<3.5mg/dL." (PMID 36248997, 2022). "However, the serum albumin level was affected by inflammation and infection processes, and little evidence supports that it is a marker of sarcopenia." (PMID 35313647, 2022). "Low albumin (3.5 ± 0.6 g/dL) and high fecal calprotectin (FC) (334.7 ± 167.2 μg/g) were observed in the presence of sarcopenia compared to 3.88 ± 0.5 (p = 0.029) and 238.95 ± 138.7 (p = 0.03) in patients without sarcopenia, respectively." (PMID 36079718, 2022). "The sarcopenia and non-sarcopenia groups differed significantly in age; body mass index; renal function; intubation time; transfusion of red blood cells; hospital transfer; and hemoglobin, brain natriuretic peptide, and albumin levels." (PMID 35313647, 2022). "However, the results of this study still presented the potential of sarcopenia as a tool for predicting survival of patient independent of other factors, including albumin, N stage and TNM stage." (PMID 35501704, 2022). "Finally, although the GNRI cut-off value was presented as screening before possible sarcopenia assessment, the serum albumin level was not adjusted for diet or dialysis dose." (PMID 34772346, 2021). "In this study, the serum albumin level of sarcopenia patients was lower than that of non-sarcopenia patients, but the difference was not statistically significant, which may be related to the small sample size included." (PMID 34654871, 2021). "In this context, it is interesting that several clinical studies could demonstrate a link between the specific pattern of increased CRP and decreased albumin concentrations with sarcopenia, frailty, and vascular and non-vascular mortality in elderly subjects." (PMID 30715588, 2019). "Sarcopenia was significantly associated with higher age, lower mean upper arm circumference, lower phase angle by BIA, lower serum levels of creatinine and hemoglobin, higher CRP, but not with differences in serum albumin, BMI or waist circumference." (PMID 30305034, 2018). "Furthermore, differences in handgrip strength (HG), fat-free mass (FFM), bone mineral content (BMC), plasma albumin (ALB) and serum creatinine (Cr), and body fat content (FAT) in patients between the sarcopenia and non-sarcopenia groups were statistically significant (P < 0.05)." (PMID 28701179, 2017). "Furthermore, patients with sarcopenia have significantly lower BMI values than patients without sarcopenia, and the serum albumin levels of these patients are generally lower." (PMID 29254263, 2017). "Interestingly, our analysis showed that protein and albumin levels were similar in patients with and without sarcopenia, indicating that these biochemical markers may not reliably reflect muscle mass or nutritional status." (PMID 40912688, 2026). "Moreover, it has been described that albumin levels may not differ among robust and frail KT candidates but sarcopenia does." (PMID 40630784, 2025).
sarcopenia (continued). "However, age, sex, serum albumin, lymphocyte ratio, and triglyceride level could not be used as influencing factors for lung cancer complicated by sarcopenia, and there was no statistical significance (P>0.05)." (PMID 40265008, 2025). "Therefore, we did not detect a relationship between serum albumin and sarcopenia." (PMID 35453410, 2022). "Albumin, CRP, vitamin D, and serum folate should not be neglected in screening for sarcopenia in the aging population." (PMID 37110223, 2023). "Albumin, CRP, vitamin D, and serum folate should not be overlooked when screening for sarcopenia in geriatric settings, particularly in the male population." (PMID 37110223, 2023). "In univariate analyses, it was found that patients in the sarcopenic group had lower weight, BMI, albumin, prealbumin, Cr/CysC ratio, and HGS, compared to those without sarcopenia." (PMID 36118766, 2022). "As for the biochemical findings, the levels of albumin (p = 0.003), BCAA (p < 0.001), and 25(OH)D (p = 0.001) in the sarcopenia group were significantly lower than those in the non-sarcopenia group." (PMID 33322706, 2020). "On the other hand, serum albumin, blood urea nitrogen (BUN), creatinine, and phosphate levels were significantly lower in those with sarcopenia than in those without sarcopenia." (PMID 30922266, 2019). "Univariable analysis showed that in addition to the presence of sarcopenia, ECOG PS ≥ 2, no response to chemotherapy, no second-line chemotherapy, low serum albumin level (< 3.5 g/dL), and metastatic sites ≥ 3 were significant prognostic factors." (PMID 30125312, 2018). "Compared with non-sarcopenia group, the sarcopenia group was found to be older and less educated, and HGB, ALT, ALB, BMI, CG, WC, and WHR were lower than those in the non-sarcopenia group, while FPG, TG, TyG, TyG-BMI, TyG-CG, TyG-WC, and TyG-WHR were higher (P < 0.05)." (PMID 40443446, 2025). "However, the sarcopenia group exhibited lower GNRI, serum albumin, SMA, SMD, SMI, SATA, and SAT indices compared to the non-sarcopenia group (p < 0.05)." (PMID 41235313, 2025). "Compared with the nonsarcopenia group, serum albumin levels were significantly lower (4.3 ± 0.3 vs. 4.4 ± 0.3, p = 0.015) and serum TNF-α levels were significantly higher (1.97 ± 0.77 vs. 1.61 ± 0.64, p = 0.008) in the sarcopenia group." (PMID 37015998, 2023). "Additionally, among the control group, controls with sarcopenia showed significant reduction in BMI, muscle mass, MAMC, and albumin compared to controls without sarcopenia (P = 0.001, P = 0.001 and P = 0.01, respectively)." (PMID 37767786, 2023). "Among laboratory test results, serum levels of albumin, calcium, alkaline phosphatase, aspartate aminotransferase (AST), and alanine aminotransferase (AST) were not significantly different either between the two groups (sarcopenia vs. non‐sarcopenia)." (PMID 34350631, 2021). "Regarding the biochemical data, hemoglobin and serum levels of total cholesterol, total protein, albumin, total calcium, and total CO2 were significantly lower, whereas serum levels of blood urea nitrogen and SCr were significantly higher in patients with sarcopenia than in those without." (PMID 34531464, 2021). "A study on geriatric trauma patients admitted to the ICU demonstrated that sarcopenia was a predictor for mortality and ICU resource utilization while other traditional measures of nutritional assessment, such as body mass index and serum albumin, failed to predict adverse outcomes." (PMID 31890363, 2019).
coronary artery disease (457 papers, 2005 to 2026). "Multivariable analyses adjusted for age, sex, BMI, admission NIHSS score, infarct location, vascular risk factors, atrial fibrillation, coronary heart disease, moderate-to-severe arterial stenosis, serum albumin, and total protein." (PMID 42306622, 2026). "Although the fibrinogen-to-albumin-to-globulin ratio (FAGR) has been proven to be related to coronary artery disease (CAD), the association between the FAGR and acute ST-segment elevation myocardial infarction (STEMI) has not been adequately investigated." (PMID 40102522, 2025). "Clinical data show that lower ALB concentrations are associated with more severe coronary artery disease, with ALB levels decreasing progressively as disease severity increases." (PMID 40809897, 2025). "The CRP/albumin ratio wasa risk factor in male patients, those aged ≥ 60 years old, and those witha BMI ≥ 25 kg/m2, coronary heart disease, or cerebralinfarction." (PMID 40622101, 2025). "While significant evidence has linked various biomarkers to cardiovascular risk, the role of the red cell distribution width to albumin ratio (RAR) in predicting coronary heart disease (CHD) remains underexplored." (PMID 41432369, 2025). "In the univariate analysis, the risk factors significantly associated with an elevated all-cause mortality risk were underlying ischemic heart disease, cerebrovascular disease, hemoglobin level, albumin, and a TG/HDL-C ratio > 3.29." (PMID 41283273, 2025). "Their stable interaction with serum albumin and balanced physicochemical properties support further development as novel agents for managing ischemic heart disease and associated inflammatory conditions." (PMID 41011122, 2025). "This research aimed to explore the association of high-sensitivity C-reactive protein to albumin ratio (CAR) with death events in community-based patients with coronary heart disease (CHD)." (PMID 40435309, 2025). "Minor traits that were linked to CYP1A2 included serum albumin levels, red blood cell count, platelet distribution width, coronary heart disease, cardiovascular disease, brain morphology, and peak expiratory flow." (PMID 39457450, 2024). "Significant differences were observed in age, age group, coronary heart disease, arrhythmia, hemoglobin levels and albumin levels upon admission, as well as intraoperative blood loss (P < 0.20) at admission." (PMID 38355490, 2024). "Previous clinical studies have established that low serum albumin is an independent risk factor for coronary artery disease." (PMID 38580915, 2024). "Age over 75, concomitant coronary artery disease, hemoglobin level below 100 g/L and albumin level below 40 g/L on admission were independent risk factors for AHF in older hip fracture patients." (PMID 38355490, 2024). "This suggests that the adverse effects of increased BUN and urinary albumin excretion on the likelihood of coronary disease are largely mediated through associated disturbances in blood pressure, glucose, and lipids." (PMID 39524990, 2024). "Low serum albumin levels are also linked to ischemic heart disease, heart failure, atrial fibrillation, stroke and inflammation." (PMID 38331757, 2024). "In another analysis of patients with coronary artery disease, lower baseline serum albumin and TC indicated a higher risk of major adverse cardiac events." (PMID 36643628, 2023). "This study aimed to assess the correlation between serum albumin levels and coronary heart disease (CHD) risk in adults aged over 45 years." (PMID 36635398, 2023). "Another study concluded that low albumin in stable coronary artery disease (CAD) is caused by atherosclerotic systemic inflammation." (PMID 37989757, 2023). "Various independent risk factors identified include age, chronic heart failure, coronary artery disease, chronic pulmonary disease, Parkinson's disease, serum albumin, and creatinine concentrations." (PMID 38143658, 2023).
coronary artery disease (continued). "A low serum albumin concentration is also strongly associated with thedevelopment of ischemic heart disease and acute myocardial infarction." (PMID 39077142, 2022). "Low serum albumin levels have been identified as a risk factor for the development of coronary artery disease; moreover, in patients with ACS, lower serum albumin levels tend to predict worse outcomes." (PMID 36286310, 2022). "Serum albumin <2 g/dL, coronary artery disease, and Hb <10 g/dL were also significantly associated with the risk of death from univariate analysis." (PMID 36091688, 2022). "Apart from the risk factors from the SCORTEN, coronary artery disease, Hb <10 g/dL, and serum albumin <2 g/dL were significantly associated with mortality of patients with SJS/TEN from univariate analysis in the present study." (PMID 36091688, 2022). "For instance, the Atherosclerosis Risk in Communities (ARIC) study involving 14,506 individuals reported a significant association of reduced blood albumin with the prevalence of ischemic heart disease." (PMID 35850629, 2022). "Epidemiological evidence showed that low serum albumin levels were linked to incident ischemic heart disease, heart failure, atrial fibrillation, stroke, and venous thromboembolism, independent of risk factors, body mass index, and inflammation." (PMID 36337861, 2022). "Epidemiologic studies have reported on associations of various inflammatory factors, including low albumin with coronary heart disease (CHD)." (PMID 35881574, 2022). "Analysis of the risk factors affecting the change in CTR and vascular calcification over time showed that an increase in AoAC, older age, female sex, coronary artery disease, and decreased albumin were associated with a greater change in CTR." (PMID 34442433, 2021). "More recently, glycated albumin has been shown as being positively correlated to HbA1c and associated with coronary heart disease, ischemic stroke, heart failure, and death." (PMID 34684632, 2021). "Low serum albumin level has been identified as a risk factor for the development of coronary artery disease." (PMID 31815281, 2020). "In DM 2 individuals with stable coronary artery disease, the levels of glycated albumin and the splice variant endogenous secretory RAGE (esRAGE) were independent predictors of primary and secondary endpoints." (PMID 33019603, 2020). "Another study showed that neutrophil-to-lymphocyte ratio was significantly associated with urinary albumin-to-creatinine ratio in asymptomatic stable coronary heart disease populations and was an independent predictor of systemic endothelial dysfunction." (PMID 32000667, 2020). "In patients with coronary artery disease, antibodies against N-homocyteinylated albumin have been detected; the presence of these antibodies was associated with early coronary artery disease." (PMID 30930689, 2019). "NEFA/Albumin is a parameter that indicating cardiovascular risks, particularly less coronary heart disease risk in trained animals." (PMID 30305835, 2018). "It is very important to explore how we can reduce urinary albumin excretion which is an independent risk factor for ischemic heart disease." (PMID 30525055, 2018). "The final model for 6-month mortality risk included older age, female gender, ischemic heart disease, and low albumin levels (articles submitted or in draft)." (PMID 29317867, 2017). "In recent years, it has been reported that a low serum albumin level is a risk factor for ischemic heart disease and cerebral infarction, which greatly influences the prognosis and quality of life of the elderly." (PMID 31011042, 2017). "In this study, we retrospectively analyzed the conditions of PF patients before PD surgery and found that the preoperative serum albumin, history of coronary heart disease, and excessive drinking were the independent risk factors associated with PF." (PMID 25788941, 2015).
coronary artery disease (continued). "A meta-analysis of 8 prospective, population-based studies on albumin and coronary heart disease (CHD) found an inverse association between serum albumin concentration and CHD risk." (PMID 23912327, 2013). "Substantial evidence support the significant inverse relation between serum albumin level and risk of coronary heart disease as well as cancer, other causes of death, and all-cause mortality." (PMID 24049653, 2012). "Lower levels of serum albumin within the “normal” range are associated with increased risk of all-cause and cardiovascular mortality, as well as with coronary heart disease (CHD) and stroke incidence." (PMID 24049653, 2012). "Epidemiological studies have shown that a highly significant inverse relationship exists between serum albumin levels and risk of coronary heart disease." (PMID 21554699, 2011). "Coronary artery disease can also cause heart failure, which lead to hepatic congestion and renal insufficiency, thereby impacting albumin metabolism and contributing to decreased albumin levels." (PMID 39624213, 2024). "This could be relevant to evaluations of the risk or prognosis of conditions such as coronary heart disease, where decreased levels of serum albumin and TAC are observed." (PMID 39590018, 2024). "Decreased serum albumin levels may trigger inflammation that causes coronary artery disease, as it activates proinflammatory cytokines." (PMID 37109621, 2023). "Maintaining normal albumin levels can reduce the risk of death from ischemic heart disease." (PMID 36873413, 2023). "Furthermore, an association has also been reported between low serum albumin level and poor prognosis among coronary artery disease patients." (PMID 34996387, 2022). "In conclusion, glycated albumin may be an important risk factor for atherosclerosis, coronary heart disease, ischemic stroke and END following AIS." (PMID 35711907, 2022). "We aimed to examine whether the efficacy of the risk of poor prognosis in patients with coronary artery disease is jointly affected by total cholesterol and baseline serum albumin in a secondary analysis of previous study." (PMID 35879423, 2022). "Moreover, low serum albumin concentration has been reported to be associated with adverse clinical outcomes of ischemic heart disease." (PMID 35686040, 2022). "We suggested that baseline serum albumin and total cholesterol could interactively affect the risk of poor prognosis of patients with coronary artery diseases." (PMID 35879423, 2022). "Increased CPP generation propensity (higher OD650 increase values) was associated with higher ionised calcium (Ca2+) and lower albumin, thereby reflecting disturbed mineral homeostasis in cohorts of patients with coronary artery disease and cerebrovascular disease compared with healthy blood donors." (PMID 34830334, 2021). "Low serum albumin levels are independently associated with the development of various diseases, such as e myocardial infarction (MI), coronary artery disease (CAD), stroke, CI-AKI, hip fracture, and malignancy." (PMID 38773489, 2024). "In the current study, we found that ASA classification, age, preoperative albumin level, preoperative hemoglobin level, operation type, preoperative coronary heart disease, and postoperative ICU admission may be risk factors associated with PD through univariate analysis." (PMID 37978346, 2023). "Similarly, low ALB has also been shown to be associated with inflammation and the risk of cardiovascular and cerebrovascular diseases, including acute coronary syndrome and stable coronary heart disease." (PMID 36457873, 2022). "Therefore, a low albumin level may reflect an underlying inflammatory state, which increases the risk of mortality in various disease processes, including coronary artery disease." (PMID 35369313, 2022). "There is also an association with coronary artery disease (CAD) and other acute phase reactants like albumin." (PMID 33094574, 2020).